MTF1 (metal regulatory transcription factor 1)
Diseases named in the same sentence as MTF1 in open-access papers (continued):
Sharing a sentence is not in itself a finding about the gene and the disease.
Sepsis (6 papers, 2020 to 2026). Sepsis is defined as life-threatening organ dysfunction caused by a dysregulated host response to infection. "FOXO1, KLHL3, and PCBP1 were weakly expressed in the sepsis group whereas MTF1, TMEM59, PIK3CB, and S100A9 were highly expressed in the sepsis group." (PMID 41542228, 2026). "The top five gene variables (MTF1, UBE2D2, DLAT, DLD, and ULK2) were selected as disease signature genes in the GLM model to construct a nomogram for predicting the incidence of sepsis-associated ALI." (PMID 38779731, 2025). "It associates directly with TDRD9 and indirectly with SLC16A3 in pediatric sepsis, through MTF1, CD82, and G6PD." (PMID 32318053, 2020). "The expression of SLC31A1, CD274, ATOX1, MTF1, UBE2D1, DLD, and VEGFA was found to be upregulated, while that of DLST, UBE2D2, COX11, DLAT, GLS, FDX1, and ULK2 were significantly downregulated in patients with sepsis-associated ALI." (PMID 38779731, 2025). "Finally, the 6 DECuGs (ANKRD9, DLD, LIPT1, MTF1, PDHB, UBE2D4) as diagnostic biomarkers for sepsis were identified by the intersection of the two machine learning algorithms." (PMID 38495196, 2024). "Next, six key DECuGs (ANKRD9, DLD, LIPT1, MTF1, PDHB, UBE2D4) were identified as diagnostic biomarkers based on the two machine learning algorithms, suggesting their potential functional importance in the pathogenesis of sepsis." (PMID 38495196, 2024). "The MTF1-T-cell CD4 memory resting cells were the most negatively correlated DECuG–immunocyte pair (r = −0.61, P-value<0.001), with a lower expression level of MTF1 and a lower infiltration of T-cell CD4 memory resting cells in sepsis." (PMID 38495196, 2024). "For immune cells, monocytes, T cells, B cells, and NK cells were related to DLD, LIPT1, MTF1, PDHB and UBE2D4 in the sepsis group." (PMID 38495196, 2024). "Furthermore, GSE236713 cohort was utilized to verify SLC31A1, MTF1, LIAS and LIPT1 level in sepsis." (PMID 39652607, 2024).
hepatocellular carcinoma (5 papers, 2016 to 2026). A malignant tumor that arises from hepatocytes. "Copper exposure considerably stimulates the proliferation of hepatocellular carcinoma (HCC) cells with enhanced MTF-1 expression." (PMID 34660270, 2021). "The level of PlGF transcripts is regulated by transcription factors, including metal responsive transcription factor 1 (MTF‐1), nuclear factor‐κB (NF‐κB) 26, 27, 28, as well as microRNA‐125b in hepatocellular cancer." (PMID 26648175, 2016). "In hepatocellular carcinoma (HCC), MTF1 may represent a potential therapeutic target to modulate metal and redox balance, opening up new avenues for cancer treatment." (PMID 40520016, 2025).
lung carcinoma (5 papers, 2013 to 2024). "Arsenic exposure is a worldwide health concern associated with an increased risk of lung cancer but arsenic trioxide (AsIII) is also an effective chemotherapeutic agent, Inactivation of ZnT1 or its transcriptional activator MTF1 resulted in considerable AsIII resistance." (PMID 38943058, 2024). "Kaplan–Meier analysis demonstrated that high MTF1 expression indicated favorable OS for the lung cancer patients treated with chemotherapy." (PMID 37380924, 2023). "By means of Kaplan–Meier plotter, we found that lung cancer patients with high expression levels of MTF1 displayed good OS, first progression (FP) and post-progression survival (PPS)." (PMID 37380924, 2023). "Similar expression pattern was found in cohort GSE32863 except for the MTF1 gene, which exhibited significantly higher expression in lung cancer tissues compared with normal tissues." (PMID 36712848, 2022). "By contrast, expression of the genes for M)-1A, MT-2A, and the metal transcription factor MTF-1 were three-fold to four-fold lower in lung cancers." (PMID 23947958, 2013). "As the diagraph depicted, the MTF1 protein levels in UCEC, lung cancer and GBM were higher than that in normal groups." (PMID 37380924, 2023). "In a word, our study showed that FDX1, a key enzyme for cuproptosis, affected the prognosis of lung cancer patients by influencing the expression of GLS, PDHA1, PDHB, DLAT, and MTF1." (PMID 36620594, 2022). "FDX1 affects the prognosis of lung cancer by altering the expression of cuproptosis-related signature (GLS, PDHA1, PDHB, MTF1, and DLAT), which more strongly confirms that the prognosis of lung cancer patients is closely related to the occurrence of cuproptosis." (PMID 36620594, 2022). "Metal-regulatory transcription factor 1 (MTF1), a conserved metal-binding transcription factor in eukaryotes, regulates the proliferation of cancer cells by activating downstream target genes and then participates in the formation and progression of tumors, including lung cancer (LC)." (PMID 38943058, 2024).
Wilson disease (5 papers, 2023 to 2025). A very rare inherited multisystemic disease presenting non-specific neurological, hepatic, psychiatric or osseo-muscular manifestations due to excessive copper deposition in the body. "This Cu-binding capacity of metallothioneins is even exploited therapeutically in the treatment of Wilson’s disease: oral application of high doses of Zn2+ causes the upregulation of metallothionein formation in enterocytes through the activation of metal regulatory transcription factor 1 (MTF1)." (PMID 38727263, 2024). "This suggests that ability of Cu to stimulate MTF1-mediated transcription of PRNP leads to higher hepatic PrP expression in Wilson disease." (PMID 39922819, 2025). "Here, metal regulatory transcription factor 1 (MTF1) offers an additional layer of explanation for the clinical use of zinc salts in conditions of copper overload such as Wilson’s disease." (PMID 41463392, 2025).
colorectal cancer (4 papers, 2022 to 2025). A primary or metastatic malignant neoplasm that affects the colon or rectum. "Inhibiting the KLF5 (Kruppel-like factor 5)/LIF (leukemia inhibitory factor)/MTF1 (metal regulatory transcription factor 1)/FPN1 (ferroportin-1) axis induces iron overload, sensitizing colorectal cancer to oxaliplatin." (PMID 39935430, 2025). "Although the mechanism of MT expression in colorectal cancer cells induced by CBD has not yet been clearly identified, CBD might directly regulate MT expression via MTF-1 or indirectly regulate MT expression by downregulating DNA methylation." (PMID 38068944, 2023).
psoriasis (4 papers, 2023 to 2025). An autoimmune condition characterized by red, well-delineated plaques with silvery scales that are usually on the extensor surfaces and scalp. "We established a genetic model for predicting psoriasis susceptibility based on three candidate cuproptosis-related genes (CRGs), MTF1, ATP7B, and SLC31A1, and found that patients can gain clinical benefits based on this model." (PMID 37091865, 2023). "We observed the expression of cuproptosis-related proteins, including ATP7B, SLC31A1, and MTF1, in psoriasis." (PMID 37091865, 2023). "Co-expression of ATP7B, SLC31A1, and MTF1 suggests that these key cuproptosis genes may jointly influence psoriasis development." (PMID 37091865, 2023). "Notably, transcriptomic analyses have revealed the significant upregulation of cuproptosis-associated genes (MTF1, ATP7B, and SLC31A1) in psoriatic patients, while additional clinical research has demonstrated elevated serum copper levels in individuals with psoriasis." (PMID 40332377, 2025). "Furthermore, it has been shown that SLC31A1 and MTF1 levels, as well as serum copper levels, were all elevated in psoriatic patients compared to controls, suggesting that SLC31A1 and MTF1 may be risk factors for psoriasis." (PMID 39652607, 2024). "Then, through establishing an RF model, we used the three candidate genes as cuproptosis regulators (MTF1, ATP7B, and SLC31A1) to predict the occurrence of psoriasis." (PMID 37091865, 2023). "To explore the correlation between key cuproptosis genes and drug sensitivity in psoriasis, we analyzed the sensitivity between ATP7B, SLC31A1, and MTF1 expression and drug sensitivity using the “pRRophetic” R package." (PMID 37091865, 2023). "The ROC curve prediction of the explored model genes (MTF1, ATP7B, and SLC31A1) showed that they could be used to reasonably predict the presence of psoriasis." (PMID 37091865, 2023). "The accumulation of intracellular copper leads to cell death, and the cuproptosis-related genes MTF1, ATP7B, and SLC31A1 are increasingly expressed in patients with psoriasis compared to patients without psoriasis." (PMID 38256115, 2024).
Zinc deficiency (4 papers, 2011 to 2025). A deficiency of the essential metal Zinc; an essential cofactor for many enzymes. "Thus, it is plausible that zinc deficiency limits MTF-1-dependent activation of myogenic genes, thereby indirectly reducing Myog and Mb expression and delaying differentiation." (PMID 41347147, 2025). "zip3, zip4, zip6, zip7, zip9, zip10, zip11, zip13, znt1, znt2, znt4, znt5, znt6, znt8, znt9 and mtf-1 mRNA levels were not altered with zinc deficiency, arsenic exposure, nor any combination tested." (PMID 28837703, 2017). "Thus, the active regulation of MT genes by MTF-1, proposed by TAFFEL, suggests that long-term inflammation and zinc deficiency may play crucial roles in the rupture, caused by either a de-stabilization or reactive changes in the sIA wall tissue." (PMID 21592412, 2011).
atherosclerosis (3 papers, 2011 to 2024). A disease characterized by the build-up of fatty material and calcium deposition in the arterial wall resulting in partial or complete occlusion of the arterial lumen. "MTF-1 is stress and metal-activated (especially zinc) TF and drives the expression of antioxidant and anti-inflammatory genes, e.g., in atherosclerosis." (PMID 21592412, 2011). "All these phenomena suggested that MTF1 might regulate copper-mediated cuproptosis of endothelial cells, and may also influence the occurrence and development of atherosclerosis through this mechanism." (PMID 37928399, 2023). "Therefore, CDKN2A, GLS, and MTF1 possess therapeutic potential for atherosclerosis." (PMID 39519014, 2024). "In early-stage atherosclerosis, genes such as ATP7A, GLS, DLD, ATP7B, and PDHA1 are highly expressed, whereas in later stages, the expression levels of FDX1, CDKN2A, SLC31A1, and MTF1 increase." (PMID 39519014, 2024).
COVID-19 (3 papers, 2023 to 2024). A disease caused by infection with severe acute respiratory syndrome coronavirus 2. "MTF1 is highly expressed in human bone marrow and lymphoid tissues, indicating that it may play a crucial role in the proliferation and differentiation of immune cells in COVID-19 induced ARDS patients." (PMID 39170609, 2024). "Utilizing violin plots, we observed that the alteration trends in the expression of hub genes within the validation dataset mirrored those in GSM172114, confirming the heightened expression of SAT1, MTF1, and TXN in the COVID-19-induced ARDS group." (PMID 39170609, 2024). "The strong relations between neutrophils and CRGs and their strongest positive and negative correlations with MTF1 and FDX1, respectively, imply that MTF1 and FDX1 may regulate neutrophil infiltration in COVID-19." (PMID 37533853, 2023).
liver cancer (3 papers, 2023 to 2025). An epithelial or non-epithelial malignant neoplasm that arises from the liver. "In summary, we first report a new antitumor mechanism of EGCG, which disrupted intracellular copper homeostasis and facilitated cuproptosis in liver cancer cells by regulating the MTF1/ATP7B axis." (PMID 40136640, 2025). "Moreover, in vitro experiments have shown that MTF1 knockdown prevents liver cancer cell proliferation, and promotes cell death." (PMID 38943058, 2024).
melanoma (3 papers, 2020 to 2023). A malignant, usually aggressive tumor composed of atypical, neoplastic melanocytes. "MELTF, also known as MTf (Melanotransferrin) or MTF1 (metal regulatory transcription factor 1), as an iron (Fe) binding transferrin homolog, is mainly expressed in melanoma and is low expression in normal tissues." (PMID 33287749, 2020). "Moreover, we detected that PD-L1 expression was positively correlated with some cuproptosis-related genes (CDKN2A, FDX1, LIPT1, and MTF1), but negatively correlated with other cuproptosis-related genes (ATP7B, DLST, and PDHA1) in an analysis of 470 melanoma patients." (PMID 35837286, 2022). "We found that the expression of FDX1, LIAS, LIPT1, DLD, DLAT, MTF1, and CDKN2A were significantly lower in melanoma than in normal tissues." (PMID 36824136, 2023).
osteoarthritis (3 papers, 2020 to 2025). A noninflammatory degenerative joint disease occurring chiefly in older persons, characterized by degeneration of the articular cartilage, hypertrophy of bone at the margins and changes in the synovial membrane. "In joints, zinc transporters are involved in degenerative pathologies; ZIP8 drives osteoarthritis progression by inducing MTF1-dependent MMP-13 expression in chondrocytes, whereas SLC30A6 variants are associated with decreased severity in rheumatoid arthritis." (PMID 41583444, 2025). "Most importantly, metal regulatory transcription factor 1 (MTF1) was identified as a transcriptional regulator of ZIP8, and osteoarthritis phenotypes were attenuated by MTF1 deficiency in cartilage." (PMID 32079226, 2020). "We recognized 22 of these genes as druggable according to the DGIdb database, such as MTF1, KLC3, STAT3, LIFR, and CBFB, making them potential targets for osteoarthritis therapy." (PMID 39796139, 2024).
Parkinson disease (3 papers, 2021 to 2024). A progressive degenerative disorder of the central nervous system characterized by loss of dopamine producing neurons in the substantia nigra and the presence of Lewy bodies in the substantia nigra and locus coeruleus. "In addition, the low expression of SCD and high expression of MTF1 were associated with systemic lupus erythematosus, parkinsons disease, and pathogenic escherichia coliinfection." (PMID 37904700, 2023). "Studies in Drosophila suggested a connection between MTF1 and Parkinson’s disease (PD), where MTF1 overexpression in parkin-mutant flies partially restores the wild type (WT) phenotype, hinting at a potential role in muscle development." (PMID 39637238, 2024). "Another research study demonstrated that in the brain MTF-1 can be involved in the stimulation of β-synuclein expression, a protein involved in the regulation of neuronal plasticity, and altered MTF-1 levels can contribute to the development of Parkinson’s and Alzheimer’s diseases." (PMID 33931586, 2021).
prostate carcinoma (3 papers, 2017 to 2025). A carcinoma that arises from epithelial cells of the prostate gland. "Additionally, MTF1 overexpression plays a significant role in the progression of various cancers, including prostate cancer." (PMID 40520016, 2025). "However, the role of MTF1 in prostate cancer remains largely uninvestigated." (PMID 40520016, 2025). "In mouse models, the knockdown of MTF1 and the knockout of ZIC2 significantly inhibited tumor growth of cadmium-transformed BPH1 (CTBPH1) cells, suggesting a potential therapeutic strategy for prostate cancer." (PMID 40520016, 2025).
acute myeloid leukemia (2 papers, 2019 to 2023). Acute myeloid leukemia (AML) is a group of neoplasms arising from precursor cells committed to the myeloid cell-line differentiation. "And we found that MTF1 expression was significantly up-regulated in glioblastoma multiforme (GBM), acute myeloid leukemia (LAML), brain lower grade glioma (LGG) and pancreatic adenocarcinoma (PAAD)." (PMID 37380924, 2023).
acute myocardial infarction (2 papers, 2024). Necrosis of the myocardium, as a result of interruption of the blood supply to the area. "In contrast, patients with acute myocardial infarction exhibit decreased levels of LIAS, PDHB, LIPT1, DLAT, and GLS, along with increased MTF1 levels." (PMID 39360273, 2024). "Significant differences in the expression of genes such as LIAS, LIPT1, DLAT, PDHB, MTF1, and GLS were observed between patients with stable coronary artery disease and those with acute myocardial infarction (AMI)." (PMID 39519014, 2024).
brain ischemia (2 papers, 2021 to 2024). Diminished or absent blood supply to the brain caused by obstruction (thrombosis or embolism) of an artery resulting in neurologic damage. "In the present paper, we demonstrated that in brain ischemia induced by tMCAO, MTF-1 represents a further mediator of endogenous neuroprotection elicited by remote limb postconditioning, induced by temporary femoral artery occlusion." (PMID 33931586, 2021). "Here we demonstrated that in brain ischemia induced by transient middle cerebral occlusion (tMCAO), MTF-1 is triggered by a subsequent temporary femoral artery occlusion (FAO) and represents a mediator of endogenous neuroprotection." (PMID 33931586, 2021).
diabetes (2 papers, 2024 to 2025). "SPI1 and MTF1 were two novel upstream ΤFs identified which have been suggested to be involved in the inflammatory cascade and insulin regulation in diabetes." (PMID 39974596, 2025). "SPI1 and MTF1 were two novel upstream transcription factors identified which have been suggested to be involved in the inflammatory cascade and insulin regulation in diabetes." (PMID 39974596, 2025).
endometrial carcinoma (2 papers, 2023). A malignant tumor arising from the epithelium that lines the cavity of the uterine body. "And the mutation frequency of MTF1 was the highest in endometrial carcinoma." (PMID 37380924, 2023). "In addition, the Cu2+ plus Elesclomol-treated group showed significantly higher gene expression levels for ACOXL-AS1 and hsa-mir-421 (p < 0.01), while low expression levels were observed for MTF1 gene and protein in two endometrial cancer cell lines (p < 0.01)." (PMID 38085674, 2023).
epilepsy (2 papers, 2023 to 2025). A brain disorder characterized by episodes of abnormally increased neuronal discharge resulting in transient episodes of sensory or motor neurological dysfunction, or psychic dysfunction. "Previously, we identified a new epilepsy-associated transcriptional control mechanism that relies on the zinc-dependent transcriptional activator metal-regulatory transcription factor-1 (MTF1)." (PMID 41389090, 2025). "Furthermore, modulation of the Zn2+-metal-regulated transcription factor 1 (MTF1)-CaV3.2 cascade reaction also impacts epilepsy." (PMID 37621773, 2023). "For instance, zinc can affect the occurrence of epilepsy by participating in the regulation of pathways involving SOD, MTF1-CaV3.2 cascade reaction, NMDA, and GABA." (PMID 37621773, 2023).
gastric cancer (2 papers, 2022 to 2024). A primary or metastatic malignant neoplasm involving the stomach. "In addition, MTF1 expression is lower in gastric cancer (GC) and is associated with a better prognosis." (PMID 39482784, 2024). "In the MTF1 gene, except for the B cell score, there was no statistical significance in gastric cancer, and the scores of other the five immune cells were extremely significant." (PMID 36140749, 2022).